SRCIN1 (SRC kinase signaling inhibitor 1)
Diseases named in the same sentence as SRCIN1 in open-access papers (continued):
Sharing a sentence is not in itself a finding about the gene and the disease.
glioma (3 papers, 2023 to 2025). A benign or malignant brain and spinal cord tumor that arises from glial cells (astrocytes, oligodendrocytes, ependymal cells). "Moreover, TTBK2, NAV1, and CTTNBP2 were protective factors for glioma, while SRCIN1, TRIO, KIF18A, and SLAIN2 were risk factors." (PMID 36979179, 2023). "TTBK2, NAV1, and CTTNBP2 were considered as protective factors, while SRCIN1, TRIO, KIF18A, and SLAIN2 were risk factors for glioma." (PMID 36979179, 2023). "Our study found that compared with normal tissues, CTTNBP2, KIF18A, NAV1, SLAIN2, and TRIO were upregulated in glioma, while SRCIN1 and TTBK2 were downregulated." (PMID 36979179, 2023). "Compared with the normal samples, except for SLAIN2, the CTTNBP2, KIF18A, NAV1, and TRIO protein expression in glioma was elevated, while SRCIN1 and TTBK2 were decreased." (PMID 36979179, 2023). "We found significant differences in the expression levels of ADD2, CTC1, SRCIN1, RORA, and ULK2 genes in gliomas of different grades, excluding VPS4A." (PMID 39698112, 2024). "Similarly, disease-free survival was found to be longer in patients with glioma with high expression of ADD2, CTC1, SRCIN1, RORA, VPS4A, and ULK2 than in those with low expression." (PMID 39698112, 2024). "Furthermore, survival analysis revealed that patients with glioma with high expression of ADD2, CTC1, SRCIN1, VPS4A, ULK2, excluding RORA, had a longer overall survival than those with low expression." (PMID 39698112, 2024).
ovarian carcinoma (3 papers, 2021 to 2023). A malignant neoplasm originating from the surface ovarian epithelium. "For example, in ovarian cancer, miR-665 targets SRCIN1, which inhibits SRC kinases to enhance the activation of MAPK/ERK and the mTOR axis to promote epithelial–mesenchymal transition (EMT) and cancer progression." (PMID 37894282, 2023). "Their data suggest that miR-665 targets SRCIN1 and the inhibition of miR-665 promotes SRCIN1 expression, leading to progression of ovarian cancer." (PMID 37894282, 2023). "For instance, miR-665 was shown to act as an oncogene in ovarian cancer by directly inhibiting SRC kinase signaling inhibitor 1 (SRCIN1) expression." (PMID 34497766, 2021).
pancreatic cancer (2 papers, 2022 to 2024). "Furthermore, suppression of SRCIN1 promoted cell multiplication, migration, and epithelial to mesenchymal transition (EMT) in pancreatic cancer cells." (PMID 36033827, 2022).
diabetes (1 paper, 2020). "This, accompanied by the involvement of SRCIN1 in also apoptosis related ERK pathway, shows some evidence that those two proteins may be involved in cell death related to diabetes." (PMID 33348610, 2020).
thrombosis (1 paper, 2021). "For instance, miR-150 facilitates endothelial progenitor cell angiogenesis and proliferation in deep venous thrombosis through targeting SRC kinase signaling inhibitor 1 (SRCIN1)." (PMID 34783290, 2021).
tumor (30 papers, 2008 to 2025). "Analysis of five-year survival in TCGA patients with SRCIN1 methylation of all selected differentially methylated CpG sites in unpaired tumor breast tissue revealed that high methylation was associated with shorter survival than low methylation (p < 0.024)." (PMID 38785978, 2024). "Secondly, we aimed to explore the association between SRCIN1 and circCCDC66 and their mechanism of involvement in tumor development." (PMID 32964035, 2020). "One such mechanism of tumor suppression in BC is represented by the p140Cap adaptor protein, encoded by the SRCIN1 gene, whose expression is associated with a significantly reduced probability of developing distant recurrence and improved overall survival, in particular in HER2-positive BC patients." (PMID 37169737, 2023). "Consistent with clinical data, SRCIN1 gain or loss of function mouse models demonstrated that p140Cap may affect tumor growth and metastasis formation by controlling the signaling pathways involved in tumorigenesis and metastatic features." (PMID 33079227, 2021). "Hypermethylation within the gene body of SRCIN1 is correlated with elevated gene expression, as evidenced by the high expression of SRCIN1 observed in tumor tissues from both the TCGA and Taiwanese cohorts." (PMID 38785978, 2024). "High expression of SRCIN1 was significantly correlated with various clinical variables, including age, histological type, tumor stage, ER status, PR status, HER2 status, TNBC status and luminal A type disease." (PMID 38785978, 2024). "As an effective tumor suppressor, SRCIN1 can suppress Src signaling pathways and downstream epidermal growth factor receptors, and focal adhesion kinases." (PMID 37924077, 2023). "SRCIN1 functions as a key mediator of Src inactivation, thereby suppressing the growth and development of a range of tumor types." (PMID 36033827, 2022). "Together, these findings thus indicated that miR-657 is able to drive NSCLC cell invasiveness, proliferation, and EMT induction by suppressing SRCIN1 expression and modulating the Slug pathway within these tumor cells in vitro." (PMID 36033827, 2022). "Here, it was explored that expression levels of SRCIN1 were reduced in NSCLC tumor tissues compared with paracancerous tissue specimens." (PMID 36033827, 2022). "This study demonstrated that the miR-181a-SRCIN1-SRC-VEGF cascade plays an important role in the regulation of tumour angiogenesis and that blocking this pathway can significantly reduce tumour angiogenesis." (PMID 33865381, 2021). "SRCIN1 gene expression strongly correlates with good outcomes in NB, due to the ability of the p140Cap protein to negatively regulate molecular pathways exploited for tumor progression." (PMID 31285546, 2020). "As a SRC-related tumor suppressor factor, SRC kinase signaling inhibitor 1 (SRCIN1) inhibits tumor progression and growth." (PMID 29739921, 2018). "As a tumor suppressor factor, SRCIN1 activates SRC tyrosine kinase (Csk) to inhibit SRC activation in tumor cells." (PMID 29739921, 2018). "The data showed that SRCIN1 expression in the tumor tissues was significantly downregulated compared to that in normal solid tissues." (PMID 29739921, 2018). "Kaplan–Meier analysis of these tumours showed that SRCIN1 amplification correlates with significantly improved survival." (PMID 28300085, 2017). "Considering the latest evidence, the biological impact of SRCIN1 on cancer, whether it contributes to tumor progression or acts as an oncogene, seems to be influenced by a range of intermediary proteins specific to various cancer types and subtypes." (PMID 38785978, 2024). "Preliminary studies have suggested that SRCIN1 may act either as an oncogene or as a tumor suppressor." (PMID 38785978, 2024).
tumor (continued). "Furthermore, human SRCIN1-flanking regions contain several genes involved in tumor initiation and progression, such as ERBB2 (17q12), BRCA1 (17q21), retinoic acid receptor-α (RARA; 17q21) and signal transducer and activator of transcription 3 (STAT3; 17q21)." (PMID 33079227, 2021). "SRCIN1 expression is a risk factor independent from the other known risk factors, such as MYCN oncogene amplification, INSS stage and age at diagnosis, recognized as the strongest indicators of aggressive tumor behavior in NB patients." (PMID 31285546, 2020). "SRCIN1 as a tumor suppressor has been proposed as a potential target in cancer studies." (PMID 33348610, 2020). "Furthermore, the expression levels of SRCIN1 and miR-150-3p in the tumor tissues of the 163 NSCLC patients were detected, and we identified a negative relationship between the miR-150-3p and SRCIN1 levels (R = 0.49, P = 0.002)." (PMID 32117734, 2020). "Here, we demonstrated that SRCIN1–SRC–VEGF cascade was one of the most important pathway to control angiogenesis in tumor, and blocked this pathway could significantly inhibit angiogenesis." (PMID 29739921, 2018). "The analysis of 200 ERBB2-amplified tumours from a large Swedish Cohort8, showed that the SRCIN1 gene is altered in 70% of cases, with 123 cases (61.5% of the total) showing a copy number (CN) gain for SRCIN1." (PMID 28300085, 2017). "Moreover, mRNA expression and SRCIN1 gene CN from 50 of the 200 ERBB2 amplified tumours were significantly correlated, giving a Pearson correlation of 0.77." (PMID 28300085, 2017). "Furthermore, increased levels of miR-20a-5p were detected in MDA-MB-231-derived exosomes, capable of modulating the tumor microenvironment by targeting SRC kinase signaling inhibitor 1 (SRCIN1) in murine bone marrow macrophages (BMMs), and thus promoting their proliferation and osteoclastogenesis." (PMID 37374142, 2023). "To summarize our findings, we present a model showing that upregulation of PPFIBP1 promotes FAK signaling and enhances MMP-2 expression via the FAK/Src/JNK axis may through interacting with SRCIN1, and subsequently enhances tumor cell migration and invasiveness." (PMID 34480020, 2021). "Furthermore, a mechanistic investigation revealed that LincRNA00494 might suppress NSCLC cell proliferation by decoying miR-150-3p, which targets SRCIN1, a tumor suppressor in the progression of cancers." (PMID 32117734, 2020). "While tumor-like cells showed low SRC, SRCIN1, and DAB2IP expression, SLA was predominantly expressed in these cells." (PMID 40917877, 2025). "The analysis confirmed that miR-150 facilitates tumor malignancy by targeting a tumor suppressor, SRCIN1 (SRC kinase signaling inhibitor 1)." (PMID 37924077, 2023). "Ectopic SRCIN1 overexpression inhibited the proliferative and invasive activity of NSCLC cell lines, thus suggesting that this gene functions as a tumor suppressor gene in this oncogenic context." (PMID 36033827, 2022). "Numerous tumor-related genes, such as HMGA2, RB1CC1/FIP200, SRCIN1, STAT3, and PTEN, are targeted by miR-20a." (PMID 33504017, 2021).
cancer (19 papers, 2008 to 2025). A tumor composed of atypical neoplastic, often pleomorphic cells that invade other tissues. "Src Kinase Signaling Inhibitor 1 (SRCIN1) is a tumor suppressor gene that suppresses cancer by inactivating Src in cancer." (PMID 34676171, 2021). "The role of SRCIN1 in cancer cell biology is a subject of debate." (PMID 38785978, 2024). "Therefore, the genomic status of SRCIN1 gene and the role of its post-transcriptional regulation in cancer are illustrated." (PMID 33079227, 2021). "The MEST-PURα interaction is pivotal for the activation of SRCIN1/RASAL1-ERK-Snail signaling and cancer metastasis." (PMID 39844051, 2025). "The binding of MEST to PURα blocked the physical interaction between PURα and the promoters of SRCIN1 and RASAL1, leading to the activation of ERK signaling and cancer metastasis." (PMID 39844051, 2025). "Taken together, our results demonstrate that MEST regulates SRCIN1/RASAL1-ERK-snail signaling and cancer metastasis in a PURA-dependent manner." (PMID 37149929, 2023). "Overall, to date, p140Cap expression by IHC on NB samples has not been studied owing to lack of available cancer tissues, but SRCIN1 mRNA expression correlates with a good outcome and is an independent prognostic marker for NB." (PMID 33079227, 2021).
psychiatric disorder (2 papers, 2017 to 2022). A disorder characterized by behavioral and/or psychological abnormalities, often accompanied by physical symptoms. "SRCIN1 has not been genetically associated with psychiatric disorders." (PMID 28713243, 2017).
SRCIN1 also shares sentences with these, for which no sentence is quoted: breast tumours (3 papers); glioblastoma (3); neurological disorders (3); non-small cell lung carcinoma (3); autism (2); schizophrenia (2); Becker muscular dystrophy (1); bipolar disorder (1); brain disorder (1); breast cancer disease (1); epilepsy (1); esophageal cancer (1); esophageal squamous cell carcinoma (1); Intellectual disability (1); Kohlschutter-Tonz syndrome (1); liver cancer (1); lung squamous cell carcinoma (1); metastatic tumor (1); neurodegenerative disease (1); uterine cancer (1).